ZNRF3 (zinc and ring finger 3)
Diseases named in the same sentence as ZNRF3 in open-access papers (continued):
Sharing a sentence is not in itself a finding about the gene and the disease.
cancer (45 papers, 2013 to 2026). A tumor composed of atypical neoplastic, often pleomorphic cells that invade other tissues. "Other tumor types with ZNRF3 mutation frequencies above 1% are those of the skin, liver, lungs, and cancers of the esophagus/stomach." (PMID 39674817, 2025). "As these novel therapeutics progress into clinical trials, it is important to uncover which RNF43 and ZNRF3 variants observed in cancers, are likely to benefit from such treatments." (PMID 39674817, 2025). "Although RING and R-Spondin domain mutations in RNF43/ZNRF3 are often considered to possess dominant-negative oncogene-like activity in cancers, our findings challenge this notion." (PMID 39674817, 2025). "In accordance, tissue-specific expression patterns of FZD homologues correlate with the incidence of RNF43 or ZNRF3 cancer mutations in those tissues." (PMID 38969364, 2024). "Using multiple cell lines and animal models, we demonstrated that loss-of-function changes of ZNRF3/RNF43 elevate EGFR signaling activity to promote cancer progression." (PMID 38260423, 2024). "We discovered that EGFR is the protein most negatively associated with ZNRF3/RNF43 expression using proteogenomic data of cancer patients, and that ZNRF3/RNF43 interact with EGFR and down-regulate EGFR through ubiquitination and degradation." (PMID 38260423, 2024). "Strikingly, RNF43 and ZNRF3 mutations are differentially distributed across cancer types, raising questions about their functional redundancy." (PMID 38969364, 2024). "Inactivating RNF43 or ZNRF3 mutations result in increased Wnt receptor levels in mammalian cells and promote the growth of numerous human cancers, including colorectal, endometrial, ovarian, pancreatic, gastric, and adrenocortical carcinomas." (PMID 37798281, 2023). "A recent study has presented that RNF43/ZNRF3 depletion mutation can contribute to live cancer tumorigenesis by modulating the differentiation of hepatocytes and the liver lipid metabolic state." (PMID 37848933, 2023). "Altogether, this data indicated that RNF43/ZNRF3 loss predisposes to cancer due to altered lipid metabolism and defective tissue regeneration (hepatocyte maturation) upon cumulative rounds of tissue damage." (PMID 35039505, 2022). "Although adrenocortical carcinoma is the only cancer type which has been documented owing to the mutation in ZNRF3." (PMID 34535145, 2021). "RNF43 and its homolog ZNRF3 are transmembrane E3 ubiquitin ligases frequently mutated in many human cancer types." (PMID 32527265, 2020). "Our discovery of PTPRK as a negative regulator of Wnt receptor turnover provides a rationale for its tumor suppressive function and reveals that in PTPRK-RSPO3 recurrent cancer fusions both fusion partners, in fact, encode ZNRF3 regulators." (PMID 31934854, 2020). "In pancreatic ductal adenocarcinoma, loss-of-function mutations of RNF43 and ZNRF3 correlated with cancer development while amplification of R-spondin genes was reported in more than 18% samples of patients affected by colorectal and endometrial cancer." (PMID 32046053, 2020). "Enhanced Wnt receptor expression due to mutational inactivation of the ubiquitin ligases RNF43/ZNRF3 recently emerged as a leading cause for cancer development." (PMID 30664649, 2019). "Inactivating gene mutations in the pathway, such as Rnf43 in pancreatic cancer and Znrf3 in adrenocortical cancer or additional cancers, have implicated new links between Wnt signaling and cancer transformation." (PMID 31167446, 2019). "Various truncating ZNRF3 mutations have been observed in cancers, but thus far their functional consequences are largely unknown." (PMID 39674817, 2025). "We explored the cBioPortal database to identify which cancers carry these defective ZNRF3 variants." (PMID 39674817, 2025).
cancer (continued). "Out of 63 cancers, we identified 12 that apparently only carry inactivating ZNRF3 mutations." (PMID 39674817, 2025). "Interestingly, these observations correlate with the differential prevalence of RNF43 and ZNRF3 mutations in human cancer subtypes originating from specific tissues." (PMID 38969364, 2024). "In addition, by examining tissue-specific expression patterns we translate FZD-specific roles to the incidence of RNF43 and ZNRF3 mutations in cancer." (PMID 38969364, 2024). "Loss-of-function mutations in Rnf43 and Znrf3 are frequently found in cancer cells." (PMID 37682999, 2023). "The E3 ubiquitin ligases RNF43/ZNRF3 are often mutated in cancer but their precise contribution to liver disease is unknown." (PMID 35039505, 2022). "Similarly, mutations of RNF43 and RNF43/ZNRF3 or RSPOs also play a pivotal role in the activation of oncogenic pathways in various cancers and determine the cancer onset." (PMID 36139498, 2022). "BRAF mutant/MSS cancers also commonly showed deletion of the RNF43 locus at 17q22, which may contribute to gene silencing and compensate for the lower RNF43 / ZNRF3 mutation rate in this cancer subgroup." (PMID 27661107, 2016). "Mutation of ZNRF3 in cancer is less frequent as compared with RNF43 mutations." (PMID 27338477, 2016). "Heterozygous loss of the RNF43 and ZNRF3 loci were identified in BRAF mutant/MSS cancers." (PMID 27661107, 2016). "Previously reported genetic and cancer-associated mutations further corroborate the functional significance of the ZNRF3ecto–Rspo2Fu1–Fu2 interface as the generic interaction mode for Rspo1–4 and ZNRF3/RNF43." (PMID 24225776, 2013). "Our finding that ZNRF3 loss or low ZNRF3 RNA abundance is associated with upregulation of cell cycle progression pathways further supports a model whereby WNT activation may promote aggressive disease in mitotically active cancers." (PMID 34716314, 2021). "The development and progression of various human cancer types have been associated with enhanced expression of Wnt receptors, attributed to the mutational inactivation of the ubiquitin ligases RNF43/ZNRF3." (PMID 40152621, 2026). "Taken together, we identify a large number of ZNRF3 mutations that activate β-catenin signaling, and better define the mode of action through which ZNRF3 and RNF43 mutations contribute to cancer formation." (PMID 39674817, 2025). "miR-93 also affects the Wnt pathway, a critical pathway in many cancers, by downregulating ZNRF3, an inhibitor of Wnt signaling." (PMID 39412136, 2025). "Transmembrane E3 ligases RNF43 and ZNRF3 selectively target specific Frizzled receptors to suppress WNT signalling, offering an explanation for the cancer tissue-specific distribution of RNF43 and ZNRF3 mutations." (PMID 38969364, 2024). "In the context of cancer, ZNRF3 and RNF43 are frequently inactivated by gene deletion, mutation, or other means." (PMID 38260423, 2024). "The most common mutation affecting downstream components in the aberrant cancer Wnt/β-catenin signaling pathway is seen in the gene-encoding adenomatous polyposis coli (APC), with such mutations being seen in RNF43-, ZNRF3-, and RSPO3-mediated cancers." (PMID 39125653, 2024). "In conclusion, our study unveils a novel ZNRF3/RNF43-EGFR signaling axis in cancer and provides critical insights into RSPO-ZNRF3/RNF43 signaling during cancer progression." (PMID 38260423, 2024). "Apart from the many studies on ZNRF3 in cancer tissues, several previous studies especially focused on the function of ZNRF3 in the adrenal gland." (PMID 39168120, 2024). "Overexpression of ZNRF3 reduces EGFR levels and suppresses cancer cell growth in vitro and in vivo, whereas knockout of ZNRF3/RNF43 stimulates cell growth and tumorigenesis through upregulated EGFR signaling." (PMID 38260423, 2024). "Loss-of-function mutations in RNF43 and ZNRF3 mediate FZD stabilisation and a WNT-hypersensitive growth state in various cancer types." (PMID 38969364, 2024).
cancer (continued). "Together with its ligand RSPO3, the LGR5 receptor promotes β-catenin signaling in cancer cells predominantly via membrane clearance of two endogenous negative regulators of β-catenin signaling: the transmembrane ubiquitin ligases ZNRF3 and RNF43." (PMID 37998393, 2023). "Cancer genomic studies have identified RNF43 and ZNRF3 as WNT pathway genes mutated in liver cancer." (PMID 35039505, 2022). "Zinc and ring finger 3 (ZNRF3) is located in the plasma membrane, which is usually correlated to cancer development." (PMID 35847032, 2022). "Loss-of-function mutation of RNF43 and ZNRF3 leads to the hyper-responsiveness of Wnt signals and deregulations of R-spondin/ZNRF3/RNF43 feedback loops which is marked by various forms of cancers." (PMID 34535145, 2021). "They showed that ZNRF3 overexpression strongly inhibits the migratory and invasive capacities of the cancer cells." (PMID 33513905, 2021). "RNF43 and ZNRF3 act as tumor suppressors and numerous mutations in the RNF43 gene were identified in cancers of various tissues, like endometrium, stomach, ovary, pancreases or colon." (PMID 32527265, 2020). "Our study reveals R-spondins as BMP receptor antagonists in development, inviting re-interpretation of the mode of action of R-spondins and ZNRF3 in stem cell and cancer biology." (PMID 33149137, 2020). "The three main conclusions of this study are i) that the transmembrane phosphatase PTPRK, whose gene is found in prominent cancer-related fusion events with the ZNRF3 negative regulator RSPO3, is itself a positive regulator of ZNRF3." (PMID 31934854, 2020). "We conclude that R-spondins are bifunctional ligands, which activate WNT- and inhibit BMP signaling via ZNRF3, with implications for development and cancer." (PMID 33149137, 2020). "The known cancer gene ZNRF3 belonging to the E3 ubiquitin ligase family was also frequent in our cohort (9% of samples)." (PMID 29879932, 2018). "From those cancers that were assessed for presence of mutation, a subset of cancers were examined for RNF43 and ZNRF3 transcript expression levels." (PMID 27661107, 2016). "Common ZNRF3 frameshift mutations were seen at P313 (C5 deletion) and G604 (G6 deletion) with 3 of each seen in BRAF mutant/MSI cancers." (PMID 27661107, 2016). "RNF43 and ZNRF3 had lower transcript expression in BRAF mutant compared to BRAF wildtype cancers and less cytoplasmic protein expression in BRAF mutant/MSI compared to other subtypes." (PMID 27661107, 2016). "Analysis revealed significantly higher expression for both RNF43 and ZNRF3 in BRAF wild type compared to BRAF mutant cancers and normal colorectal mucosa samples (p<0.0001 for both genes)." (PMID 27661107, 2016). "Recent studies suggest that the R-spondin-ZNRF3/RNF43 signaling module is frequently disrupted in cancer." (PMID 27338477, 2016). "Overall this study has identified that the E3 ubiquitin ligases, RNF43 and ZNRF3, are frequently mutated in BRAF mutant cancers of the serrated pathway, particularly those that are MSI." (PMID 27661107, 2016). "Mouse genetic studies have supported a critical role of the R-spondin-ZNRF3/RNF43 signaling module in cancer." (PMID 27338477, 2016). "In this review, we will discuss the biology of the R-spondin-ZNRF3/RNF43 signaling module, cancer-associated alterations of this signaling module, and their value as biomarkers to identify Wnt-addicted tumors." (PMID 27338477, 2016). "ZNRF3 was mutated in 16/54(30%) BRAF mutant/MSI and 5/33(15%) BRAF mutant/microsatellite stable compared to 0/27 BRAF wild type cancers (p=0.004)." (PMID 27661107, 2016). "This study suggests inactivation of RNF43 and ZNRF3 is important in serrated tumorigenesis and has identified a potential therapeutic strategy for this cancer subtype." (PMID 27661107, 2016).
cancer (continued). "Although the counterpart has not been studied comprehensively in the mammalian system, the mutations of RNF43, ZNRF3 and RSPO2/3 in cancer supports the importance of this mechanism to fine-tune cell responsiveness to Wnt." (PMID 25208913, 2014). "Thus, LGR4/5 and ZNRF3 are required for RSPO4-induced suppression of Wnt/β-catenin signaling in cancer cells." (PMID 41522353, 2026). "ZNRF3-mutant CRCs carrying additional APC truncations or oncogenic CTNNB1 mutations classically linked to β-catenin activation, are only observed in 5 and 1 cancer, respectively." (PMID 39674817, 2025). "A second group of cancers acquires mutations in the homologous RNF43 and ZNRF3 genes." (PMID 39674817, 2025). "In addition, we have better defined the mode of action through which ZNRF3 and RNF43 mutations contribute to cancer formation, including at endogenous expression levels." (PMID 39674817, 2025). "Importantly, in cancer patients, ZNRF3 and RNF43 are frequently inactivated by gene deletion or loss-of-function mutations." (PMID 38260423, 2024). "Further work should explore the extent to which EGFR and WNT receptors (Frizzled and LRP5/6) each transmit the effect of ZNRF3/RNF43 deactivation at different cancer stages and investigate the efficacy of blocking both EGFR and WNT signaling in treatment of ZNRF3/RNF43-deactivated tumors." (PMID 38260423, 2024). "Moreover, ZNRF3 downregulation has also been observed in many other human cancer cell lines or tissues." (PMID 39168120, 2024). "ZnRF3 overexpression increases apoptosis, and fewer cancer cells are proliferating than usual." (PMID 38313020, 2024). "Consequently, our data point to druggable vulnerabilities of specific FZD receptors in RNF43- or ZNRF3-mutant human cancers." (PMID 38969364, 2024). "ZnRF3 protein, an E3 ubiquitin ligase, is altered or removed in cancer and inhibits Wnt signaling." (PMID 38313020, 2024). "Additionally, we substantiated our findings in multiple cell lines, human cancer cell xenograft models, and genetically engineered mouse models, wherein the loss of ZNRF3/RNF43 resulted in elevated EGFR levels and facilitated cancer progression." (PMID 38260423, 2024). "WNT hypersensitivity has emerged as a major driver of cancer growth, which may be caused either by mutational inactivation of RNF43/ZNRF3 or overexpression of RSPO-fusion proteins." (PMID 38969364, 2024). "However, our proteogenomic studies have revealed EGFR as the protein most negatively correlated with ZNRF3/RNF43 mRNA levels in multiple human cancers." (PMID 38260423, 2024). "However, in cancer cells, alterations such as recurrent RSPO gene fusion or ZNRF3/RNF43 deletion or mutations disrupts this feedback loop, resulting in hyperactive WNT signaling and subsequent cancer development and progression." (PMID 38260423, 2024). "Although somatically frequently mutated in cancer, germline variants in ZNRF3 have not been established as causative for neurodevelopmental disorders (NDDs)." (PMID 39168120, 2024). "CTNNB1 and ZNRF3 were the most prevalent altered cancer-related genes." (PMID 38023213, 2023). "It has also been found that ZNRF3 hinders the growth of cancer cells and promotes cell apoptosis by regulating the Wnt/β-Catenin/TCF signaling pathway for the reason that Wnt-1 inhibits apoptosis by blocking mitochondrial cytochrome C release, thereby inhibiting the activity of caspase-9." (PMID 35847032, 2022). "In addition to frequent loss of heterozygosity of ZNRF3 occurring in the BRAF mutant/MSS cohort, one of these cancers harboured a homozygous deletion spanning approximately 170kb and including the C terminal half of the ZNRF3 locus." (PMID 27661107, 2016). "Indeed, mutations of RNF43/ZNRF3 and recurrent translocations of RSPO2/RSPO3 have recently been identified in various cancers." (PMID 27338477, 2016). "Our understanding of the R-spondin-ZNRF3/RNF43 signaling module in cancer is still evolving." (PMID 27338477, 2016).
cancer (continued). "We hypothesized that in serrated pathway cancers where APC mutation is uncommon, inactivation of RNF43 and/or ZNRF3 would present an alternate mechanism for activating the Wnt signal." (PMID 27661107, 2016). "Similarly, transcript expression of ZNRF3 mutant cancers was significantly lower than ZNRF3 wild type cancers (average of 6.16 and 7.02 respectively; p=0.009)." (PMID 27661107, 2016). "The novel combination of Porcupine and MEK inhibition synergistically inhibited RKO cell growth by more than 90%, which suggests this may be a promising therapeutic strategy to treat BRAF / RNF43 / ZNRF3 mutant serrated pathway cancers." (PMID 27661107, 2016). "The Cancer Genome Atlas Network in 2012 reported Wnt/β-catenin pathway mutations in up to 93% of colorectal cancers, and that was prior to the identification of RPSO2/3 translocations and RNF43/ZNRF3 mutations in the Wnt pathway." (PMID 25208913, 2014). "Therefore, ZnRF3 may negatively affect Wnt and Hedgehog proliferation pathways, thereby regulating cancer progression." (PMID 38313020, 2024). "Therefore, our study focused on elucidating ZNRF3/RNF43-regulated signaling pathways in cancer." (PMID 38260423, 2024). "Further research on ZNRF3/RNF43 regulation of EGFR versus WNT receptors in different cancer stages can contribute to a comprehensive understanding of RSPO-ZNRF3/RNF43 signaling in cancer progression and provide valuable knowledge for potential therapeutic interventions." (PMID 38260423, 2024). "Consequently, ZNRF3 peradventure inhibits cancer cell invasion." (PMID 35847032, 2022). "Furthermore, ZNRF3 may also restrain the migration and invasiveness of some cancer cells like papillary thyroid carcinoma cells by this pathway." (PMID 35847032, 2022). "However, not all the cancer types previously associated with downstream Wnt pathway mutations harbor RNF43/ZNRF3 mutations." (PMID 27338477, 2016). "Furthermore, the novel combination of Porcupine and MEK inhibition resulted in considerable growth reduction, which indicates this may be a promising treatment approach for patients with serrated pathway cancers harbouring RNF43 and/or ZNRF3 mutations." (PMID 27661107, 2016). "Together, these data suggest ZNRF3 and RNF43 as novel E3 ubiquitin ligases of EGFR and establish the inactivation of ZNRF3/RNF43 as a driver of increased EGFR signaling, ultimately promoting cancer progression." (PMID 41960900, 2026). "To elucidate novel signaling pathways regulated by ZNRF3/RNF43 in cancer, we conducted integrative proteogenomic analyses of human cancer datasets using LinkedOmics." (PMID 38260423, 2024). "ZNRF3 and RNF43 are closely related transmembrane E3 ubiquitin ligases with significant roles in development and cancer." (PMID 38260423, 2024). "Conversely, overexpression of ZNRF3 and RNF43 suppresses cancer cell proliferation, migration and invasion, and drug resistance in multiple human cancer cell lines." (PMID 38260423, 2024). "In contrast to these studies, our data suggested that the most prevalent altered cancer-related genes were CTNNB1 (16%) and ZNRF3 (16%)." (PMID 38023213, 2023). "The most prevalent altered cancer-related genes were CTNNB1 (16%) and ZNRF3 (16%), followed by EGFR (11%), JARID2 (11%), KMT2B (11%), KMT2C (11%), NSD1 (11%), PIK3CA (11%), SH2B3 (11%), and UBR5 (11%)." (PMID 38023213, 2023). "Therefore, ZNRF3 negatively regulates the Wnt pathway and may inhibit cancer cell growth." (PMID 35847032, 2022). "More studies are needed to characterise the role of RNF43/ZNRF3 in NAFLD development and cancer progression." (PMID 35039505, 2022). "RNF43, ZNRF3, RSPO2 or RSPO3 alterations in breast, colorectal, gastric, pancreatic and other cancers activate the Wnt/β-catenin signaling." (PMID 29312609, 2017). "Discovery of the R-spondin-ZNRF3/RNF43 signaling module and its genetic alterations in cancers represents a breakthrough in this area." (PMID 27338477, 2016).